IER3 (immediate early response 3)
Description:
May play a role in the ERK signaling pathway by inhibiting the dephosphorylation of ERK by phosphatase PP2A-PPP2R5C holoenzyme. Also acts as an ERK downstream effector mediating survival. As a member of the NUPR1/RELB/IER3 survival pathway, may provide pancreatic ductal adenocarcinoma with remarkable resistance to cell stress, such as starvation or gemcitabine treatment.
Synonyms: DIF2; IEX1; PRG1; IEX-1; DIF-2; IEX-1L; GLY96
Tractability: Antibody: UniProt predicts a signal peptide or a membrane-spanning region. PROTAC: ubiquitination databases record sites on it.
Gene: Protein-coding gene on chromosome 6 (30,743,199 to 30,744,550, reverse strand). Ensembl gene ENSG00000137331.
Subcellular location: Membrane
Pathways (Reactome):
Signal Transduction: PI5P, PP2A and IER3 Regulate PI3K/AKT Signaling
Gene Ontology:
Molecular function: protein binding
Biological process: DNA damage response; anatomical structure morphogenesis; apoptotic process; negative regulation of apoptotic process
Cellular component: nucleus; cytosol; membrane
Genetic constraint (gnomAD): Loss-of-function variants: 6 observed, 5.17 expected, observed/expected ratio (o/e) 1.16, 90% interval 0.62 to 1.86. That is too few expected variants to judge how well the gene tolerates losing a copy. Missense variants: 157 observed, 205.61 expected, observed/expected ratio (o/e) 0.76, 90% interval 0.67 to 0.87. Synonymous variants: 81 observed, 95.69 expected, observed/expected ratio (o/e) 0.85, 90% interval 0.71 to 1.02.
Homologues: Orthologues: macaque IER3 (88% identical), pig IER3 (87% identical), rabbit IER3 (81% identical), dog IER3 (78% identical), rat Ier3 (75% identical), mouse Ier3 (72% identical), guinea pig IER3 (70% identical), zebrafish zgc:158343 (30% identical).
Diseases named in the same sentence as IER3 in open-access papers:
IER3 is named in the same sentence as 93 diseases in open-access papers, as found by Europe PMC text mining. Sharing a sentence is not in itself a finding about the gene and the disease. The quoted sentences say what the papers report.
viral infection (9 papers, 2016 to 2025). "Proteins encoded by IER3 are stimulated by multiple stressors, including viral infection and IL‐1β, and play a complex role in cell cycle regulation and apoptosis for multiple cell types." (PMID 37078407, 2023). "Immediate Early Response 3 (IER3), also known as Immediate Early X gene 1 (IEX-1), is induced by various stimuli, including growth factors, cytokines, ionizing radiation, viral infections, and other types of cellular stress." (PMID 40299640, 2025). "The expression of the early response gene immediate early response 3 (IER3), formerly known as IEX-1, is induced by a wide variety of stimuli, such as growth factors, cytokines, ionizing radiation, viral infection, and other types of cellular stress." (PMID 38737277, 2024). "The expression of the early response gene immediate early response 3 (IER3) is stimulated by numerous stimuli, including growth hormones, cytokines, ionizing radiation, viral infection, and other forms of cellular stress." (PMID 37354485, 2023). "Immediate early response gene 3 (IER3), also known as IEX-1, Dif-2, gly96 or p22/PRG-1, is a stress-inducible gene, which is rapidly regulated by multiple factors, including transcription factors, inflammatory cytokines, viral infection, chemical carcinogens, growth factors and hormones." (PMID 30249226, 2018).
pancreatic cancer (8 papers, 2017 to 2025). "IER3 is highly expressed in a variety of tumors and is associated with poor prognosis, such as bladder cancer, pancreatic cancer, breast cancer, melanoma, etc.." (PMID 31832020, 2019). "At present, some research teams have studied the role of IER3 in tumors, including liver cancer, bladder cancer, and pancreatic cancer." (PMID 35291486, 2022). "The expression of IER3 was significantly correlated with advanced stage and pathological grade in pancreatic cancer." (PMID 35291486, 2022). "In this study, it was shown also that NUPR1 protected pancreatic cancer cells from apoptosis through a pathway dependent on transcription factor Relb and immediate early response 3 (IER3)." (PMID 29156578, 2017). "Furthermore, studies have highlighted the prognostic value of IER3 in several pathological conditions, including pancreatic cancer, hepatocellular carcinoma, and acute kidney injury." (PMID 40964162, 2025). "The growing body of evidence suggests that IER3 is correlated to the prognosis of various cancers, including bladder cancer, ovarian cancer, and pancreatic cancer." (PMID 35291486, 2022). "The roles of IER3 sustaining ERK1/2 phosphorylation and promoting the tumor development were found in pancreatic cancer, lung adenocarcinoma and Hodgkin lymphoma." (PMID 30249226, 2018).
breast carcinoma (7 papers, 2013 to 2025). "Notably, during the developmental trajectory of cells, breast cancer stem cells (BCSCs) tend to express genes such as IER3 and GADD45B at the early stage, while genes like NNMT and LDHB are preferentially expressed in the BCSCs-2 developmental state." (PMID 40092692, 2025). "In breast cancer, estrogen was reported to effectively up-regulated the expression of IER3." (PMID 30249226, 2018). "The established breast cancer relevance for AREG, WT1, and IER3 is discussed in a previous transcript profiling study." (PMID 23758962, 2013).
cervical carcinoma (7 papers, 2018 to 2025). A carcinoma arising from either the exocervical squamous epithelium or the endocervical glandular epithelium. "It has been reported that lncRNA GAS5 decreased radioresistance through miR-106b/IER3 in cervical cancer." (PMID 35600868, 2022). "Here, utilizing cervical carcinoma and neuroblastoma (NB) cell lines as model systems we characterized the pathways that mediate the functional switch between the oncogenic and tumor suppressor roles of IER3." (PMID 40090972, 2025). "Thus, it was recently reported that IER3 induces the apoptosis of cervical cancer cells and that its expression is downregulated in patients with cervical cancer via its ubiquitination, followed by proteasomal degradation." (PMID 36982814, 2023). "Furthermore, IER3 induced apoptosis in cervical cancer cells, and its expression was downregulated in patients with cervical cancer." (PMID 35291486, 2022). "Indeed, when overexpressed, GAS5 enhanced the sensitivity of cervical cancer cells to treatment by up-regulating IER3 through mir-106b, proving the existence of an axis of GAS5-miR-106b-IER3 regulating radio-resistance in cancer cells." (PMID 33803151, 2021). "This pattern is highly reminiscent of the product of the immediate early gene X1 (IEX-1/IER3), which was previously reported to sequester MCL-1 in response to DNA damage, at least partially co-localizing with PML bodies in HeLa cervical carcinoma cells." (PMID 30123424, 2018).
bladder cancer (6 papers, 2018 to 2025). "IER3 plays a key role in the development of cancer and can be used as a prognostic predictor for some tumors, such as bladder cancer, liver cancer, and ovarian cancer." (PMID 39377902, 2025). "Blocking the IER3/Nrf2 pathway significantly enhances the effect of antitumor drugs on bladder cancer." (PMID 38647235, 2024). "High IER3 expression was significantly correlated with high pathological lymph node staging, and the life expectancy of patients with bladder cancer with overexpressed IER3 was shorter." (PMID 35291486, 2022). "IER3 protein was mainly expressed in the cytoplasm in bladder cancer cell." (PMID 30249226, 2018). "However, the involvement of IER3 in human bladder cancer (BCa) has not been elucidated." (PMID 30249226, 2018).
endometriosis (6 papers, 2019 to 2025). The growth of functional endometrial tissue in anatomic sites outside the uterine body. "In the microenvironment level, another research group reported the importance of the H19/miR-342-3p/IER3 pathway in reducing the risk of endometriosis through suppressing Th17 cell differentiation." (PMID 40792071, 2025). "Therefore, we hypothesized that NF-κB promotes the development of endometriosis by targeting IER3 expression induced by inflammation and oxidative stress." (PMID 39377902, 2025). "H19 has been shown to regulate several pathways that are important in endometriosis, IGF1R, ITGB3, IER3, and ACTA2." (PMID 36232884, 2022). "AEBP1 and HOXB6, together with IGF-1, CYP11A1, MMP-2, CC2D2A, IER3, STX18, maybe staging markers for endometriosis." (PMID 36532015, 2022).
colorectal cancer (5 papers, 2022 to 2025). A primary or metastatic malignant neoplasm that affects the colon or rectum. "An examination of genetic information from patients with colorectal cancer disclosed that IER3 and AGRN, which play essential roles in the glycolytic pathway, are notably upregulated in colorectal cancer and are linked to reduced survival rates among patients." (PMID 41311582, 2025). "Moreover, an examination of genes linked to glycolysis has shown that IER3 and AGRN are significantly overexpressed in colorectal cancer and correlate with lower survival rates among patients." (PMID 41311582, 2025).
hepatocellular carcinoma (5 papers, 2021 to 2025). A malignant tumor that arises from hepatocytes. "IER3 is a potential prognostic factor in patients with hepatocellular carcinoma and acute myeloid leukemia." (PMID 37422626, 2023). "Immediate early response 3 (IER3) is correlated to the prognosis of several cancers, but the precise mechanisms underlying the regulation by IER3 of the occurrence and development of hepatocellular carcinoma (HCC) remain unknown." (PMID 35291486, 2022). "Four genes, CD14, NPC2, IER3, and GZMA, have been extensively investigated in hepatocellular carcinoma." (PMID 37354485, 2023).
ovarian carcinoma (5 papers, 2018 to 2025). A malignant neoplasm originating from the surface ovarian epithelium. "In a study of the female reproductive system, IER3 expression and the cancer stage were independent predictors of OS in patients with ovarian cancer." (PMID 35291486, 2022). "AGPAT1, B2M, BASP2, IER3, and IL1B are the salivary mRNAbiomarkers for ovarian cancer detection." (PMID 37693919, 2022).
Hypertension (4 papers, 2017 to 2024). The presence of chronic increased pressure in the systemic arterial system. "Arlt and Schäfer indicated that the ablation of IER3 can induce changes in BP control and hypertension in mice." (PMID 35740428, 2022). "Although IER3 is expressed ubiquitously, a constitutive IER3 knock-out mouse exhibits a cardiac phenotype with hypertension and cardiac hypertrophy, indicating that the function of this gene is important for the cardiovascular system." (PMID 28353642, 2017). "Its expression is significantly upregulated in the myocardial tissues of mice subjected to pressure overload, and IER3 gene knockout may lead to hypertension and cardiac hypertrophy in mice." (PMID 38439898, 2024).
Obesity (4 papers, 2016 to 2025). Accumulation of substantial excess body fat. "The high expression of IER3 in macrophages may facilitate this transformation, thereby promoting the onset of obesity-related inflammation and enhancing insulin sensitivity in murine models." (PMID 40964162, 2025). "The high expression of IER3 in macrophages can promote the transformation of macrophages from AAM to CAM, and promote the occurrence of obesity-related inflammation." (PMID 37153000, 2023).
heart failure (3 papers, 2017 to 2024). Inability of the heart to pump blood at an adequate rate to meet tissue metabolic requirements. "Transferase dUTP nick end labeling (TUNEL) and ssDNA stainings showed induction of apoptosis in titin-deficient cardiomyocytes during heart failure development, while IER3 response was dysregulated." (PMID 28353642, 2017). "To investigate the role of IER3 signaling in heart failure, we analyzed IER3 expression during DCM development in heterozygous titin-deficient mice." (PMID 28353642, 2017). "On the other hand, the critical role of IER3 in heart failure may intersect with the development of pediatric arrhythmias, suggesting that potential common signaling pathways or genetic variations exist." (PMID 38994496, 2024). "Targeting the IER3 pathway to reduce cardiac apoptosis might be an effective therapeutic strategy to combat heart failure." (PMID 28353642, 2017). "However, the role of IER3 in heart failure, and particularly in titin-based dilated cardiomyopathy, has not been investigated so far." (PMID 28353642, 2017). "Here, we investigate the role of IER3 in an inducible heart failure mouse model." (PMID 28353642, 2017). "Blunted IER3 response may be an important mechanism for heart failure in our mouse model." (PMID 28353642, 2017). "Microarray results also revealed common induction of transcription factor-coding genes whose modulation in response to CPB has not been described, among which IER2, IER3, and FOSL2 play critical role in cardiac remodeling and apopotosis, myocardial dysfunction, and heart failure." (PMID 31924244, 2020).
multiple myeloma (3 papers, 2010 to 2025). "Small interfering RNA for three up-regulated genes (BNIP3, IER3, and SEPW1) affected critical multiple myeloma endothelial cell functions mediating the cell overangiogenic phenotype, that is proliferation, apoptosis, adhesion, and capillary tube formation." (PMID 27713297, 2010). "Validation was focused on DIRAS3, SERPINF1, SRPX, BNIP3, IER3, and SEPW1 genes, which were not previously found to be functionally correlated to the overangiogenic phenotype of multiple myeloma endothelial cells." (PMID 27713297, 2010).
neuroblastoma (3 papers, 2010 to 2025). Neuroblastoma (NB) is the most common solid, extracranial childhood tumor.
tongue cancer (3 papers, 2019 to 2022). A malignant neoplasm affecting the tongue. "In this study, we identified that IER3 was an important gene associated with lymph node metastasis and prognosis in tongue cancer patients by analyzing the GSE2280 RNA microarray dataset and the TCGA tongue cancer RNA-seq dataset." (PMID 31832020, 2019). "More importantly, tongue cancer patients with lymph node metastasis showed significantly higher expression of IER3, and high expression of IER3 showed better recurrence-free survival." (PMID 31832020, 2019). "We examined the protein expression of IER3 in 2 tongue cancer cell lines and 2 oral squamous cell carcinoma cell lines, and the results showed that all 4 oral cancer cell lines expressed IER3." (PMID 31832020, 2019). "IER3 was proved mediated cancer development in many cancers including tongue cancer." (PMID 36568368, 2022). "More importantly, we found that knocking down IER3 reduced the secretion of VEGF-C from tongue cancer cells, which could promote the formation of lymphatic vessels and lymph node metastasis." (PMID 31832020, 2019). "Gene coexpression network analysis and survival analysis further confirmed that IER3 was the key gene associated with the prognosis and lymph node metastasis of tongue cancer patients." (PMID 31832020, 2019). "We found that IER3 might be a key gene that promotes the progression and lymph node metastasis of tongue cancer." (PMID 31832020, 2019). "We found that IER3 could promote the proliferation, invasion and migration of tongue cancer cells in vitro." (PMID 31832020, 2019). "We validated the function of IER3 in tongue cancer cells, and the results showed that knocking down IER3 significantly decreased the proliferation, migration and invasion of Tca-8113 cells and decreased the secretion of VEGF-C, which reduced the tube formation and migration of LECs." (PMID 31832020, 2019). "Our study demonstrated that IER3 plays important roles in lymphangiogenesis regulation and prognosis in tongue cancer and might be a potential therapeutic target." (PMID 31832020, 2019). "Our study found that high expression of IER3 was associated with poor prognosis and lymph node metastasis in patients with tongue cancer, suggesting that IER3 might have a cancer-promoting effect in tongue cancer." (PMID 31832020, 2019). "We then investigated the roles of IER3 in tongue cancer cells by performing proliferation, migration and invasion assays, and we also demonstrated that IER3 could promote lymphangiogenesis in vitro." (PMID 31832020, 2019). "Furthermore, IER3 was found to play an important role in the regulation of lymph angiogenesis and in the prognosis of tongue cancer; it may, therefore, be a therapeutic target." (PMID 35291486, 2022). "The activation of the PI3 K/AKT and JAK2/STAT3 signaling pathways could promote the secretion of VEGF-C in cancer cells, suggesting that IER3 might induce the generation of VEGF-C in tongue cancer cells, but the specific molecular mechanism needs to be identified in further studies." (PMID 31832020, 2019). "Moreover, based on TCGA data, we found that IER3 was the key gene that might promote lymph node metastasis and a potential marker of prognosis for tongue cancer patients." (PMID 31832020, 2019). "More importantly, we found that the hub gene IER3 might predict prognosis tongue cancer, and our in vitro experiments demonstrated that IER3 might promote the progression and lymph node metastasis in tongue cancer, which might be a potential therapeutic target." (PMID 31832020, 2019). "Previous studies have reported that IER3 is involved in the activation of the PI3 K/AKT and MAPK/ERK signaling pathways, which promotes tumor progression, also suggesting that IER3 plays a role in promoting tongue cancer, but further in vivo evidence is needed." (PMID 31832020, 2019).
atherosclerosis (2 papers, 2019 to 2024). A disease characterized by the build-up of fatty material and calcium deposition in the arterial wall resulting in partial or complete occlusion of the arterial lumen. "IER3 is an NF-κB-responsive gene similar to TNFAIP3, which is also upregulated in atherosclerosis, inhibited endothelial neogenesis, and has an anti-myocardial hypertrophic function." (PMID 39234566, 2024). "Though CTA-384D8.35, CTB-114C7.4 and miR-4497 have not been studied yet, their functions could be interpreted by their target genes in the ceRNA network, including inflammatory responses (CCL3, ZFP36, IER3), apoptosis (EGR1), atherosclerosis and myocardial ischemia (FOS)." (PMID 31443660, 2019).
colitis (2 papers, 2016 to 2020). Inflammation of the colon. "Some of these genes have also been associated with an abnormal response to infection (C4A, ENSBTAG00000006864, and IER3), increased/decreased susceptibility to bacterial infection (C4A and ENSBTAG00000006864), or induced colitis (ABCC4 and IER3)." (PMID 32183688, 2020).
diabetes (2 papers, 2023 to 2025). "The heatmap illustrates significant correlations between IER3 and genes involved in the PI3K/Akt and MAPK signaling pathways associated with diabetes." (PMID 40964162, 2025).
glioblastoma (2 papers, 2019 to 2022). The most malignant astrocytic tumor (WHO grade IV). "Overexpression of IER3 sensitizes glioblastoma cells to γ-radiation-induced apoptosis." (PMID 31541175, 2019). "In this study, the results showed that CTSD and IER3 were predominantly expressed in myeloid cells, high expression of AP1S1 was shown in glioblastoma cells, and YWHAG was mainly expressed in glioblastoma cells, oligodendrocytes, and myeloid cells." (PMID 35892430, 2022). "CTSD expression was highest in myeloid cells, high expression of AP1S1 was shown in glioblastoma cells, and YWHAG was mainly expressed in glioblastoma cells, oligodendrocytes, and myeloid cells, and IER3 was predominantly expressed in myeloid cells." (PMID 35892430, 2022).
lung carcinoma (2 papers, 2022 to 2024). "IER3 was an inhibitor of apoptosis, and higher expression of IER3 contributed to the progression of lung cancer." (PMID 36311764, 2022).